VHL (von Hippel-Lindau tumor suppressor)
Diseases named in the same sentence as VHL in open-access papers (continued):
Sharing a sentence is not in itself a finding about the gene and the disease.
tumor (continued). "Four tumor suppressor genes map in this region: VHL in 3p.25, PBRM1 (subunit of the PBAF SWI/SNF chromatin remodeling complex), BAP1 (histone deubiquitinase), and SETD2 (histone methyl transferase) in 3p.21." (PMID 36902045, 2023). "Consistent with the RC model, renal tumors with AC-VHL-WT or 1:1 mixed of VHL-WT and VHL-KO cells grew well, but lung metastasis was observed only in mice bearing the mixed-tumor group." (PMID 37069149, 2023). "Overexpression of UBE2S promotes tumor cell proliferation and migration by regulating the VHL/HIF-1α/STAT3 signaling pathway." (PMID 38115063, 2023). "VHL is an important tumor suppressor that is lost in the majority of ccRCC cases, acting as a component of E3 ligase mediating HIF degradation." (PMID 37460463, 2023). "Multiorgan tumors are a hallmark of the autosomal dominant genetic disorder known as Von Hippel-Lindau syndrome (VHL), which is typically the result of inherited aberrations of the VHL tumor suppressor gene." (PMID 37251595, 2023). "Since VHL plays a tumor-suppressing role, this connection validates the value of the calculated risk score from another perspective." (PMID 37025600, 2023). "POSTN enhances the motility of VHL+ cells and the dissemination of tumor cells by disrupting the vasculature." (PMID 37069149, 2023). "As expected, HIF composite scores were significantly elevated in ccRCC tumours compared with patient-matched normal kidney (P = 6 × 10−13), confirming constitutive HIF activation in these tumours as a result of VHL loss." (PMID 36725335, 2023). "Overexpression of FTO in VHL-deficient RCC restored mitochondrial activity, induced oxidative stress and ROS production, and restrained tumour proliferation by increasing the expression of PGC-1α." (PMID 37284313, 2023). "PE (18:2-19:1) significantly stimulated the proliferation, migration and invasion of 4T1 and MDA-MB-231 cancer cells in a dose-dependent manner, suggesting the pro-tumour effect of PE mediated by miR-204/VHL mediated leptin signalling pathway." (PMID 37620316, 2023). "The VAFs of somatic VHL mutations in the TCGA KIRC cohort (n = 148), after adjusting for tumor purity and ploidy, also displayed a wide spectrum spanning between 0.5 and 1, indicating subclonal mutations." (PMID 37069149, 2023). "Previous studies have shown that UBE2S can regulate tumor development through the VHL/HIF‐1α signaling pathway." (PMID 37563971, 2023). "Our study was the first to demonstrate the association between VHL levels and clinico-pathological parameters in PTC, providing evidence of the involvement of VHL tumor suppressor in PTC pathology." (PMID 36036061, 2023). "The impact of L169P VHL on tumor growth suppression was again comparable to WT VHL in slowing the growth of VHL-null 786-O cells in cultures as well as in xenografts in a CAM model." (PMID 37762376, 2023). "Paralleling the preclinical scenario, the MIF stain of the #22 primary tumor showed a predominance of VHL+ cells within the vasculature." (PMID 37069149, 2023). "PBRM1 is a bona fide tumor suppressor in ccRCC in the context of VHL deletion; however, in other cancer contexts, it is oncogenic and a proposed therapeutic target." (PMID 36808431, 2023). "The CNR at the VHL locus was analyzed in the TCGA KIRC (Kidney Renal Clear Cell Carcinoma) cohort (n = 459) after adjusting for both tumor purity and ploidy." (PMID 37069149, 2023). "In another study, FTO was found to be downregulated in Von Hippel-Lindau (VHL)-deficient RCC tissue and correlated with tumour severity and poor prognosis." (PMID 37284313, 2023). "The potential impact of VHL and PRBM1 mutations on the expression of CXCL genes and their tumor suppression function were also investigated." (PMID 37540227, 2023). "A primary tumor cell line was generated from case #22, which consisted of an equal mixture of VHL+ and VHL− tumor cells upon initial tumor dissociation (P0)." (PMID 37069149, 2023).
tumor (continued). "Reduced HIF1A but conversely elevated VHL abundance was measured in both eWAT and iWAT from 4T1/miR-204 KO mice comparing tumour bearing mice." (PMID 37620316, 2023). "The benefit was reinforced by the marked reduction in the interventions required for VHL-related neoplasm indications following the initiation of belzutifan." (PMID 36980625, 2023). "They established the pNET as a distinct tumor type of the VHL disease by demonstrating the presence of VHL allelic deletion genes, which provides evidence for the role of genes in tumorigenesis." (PMID 37251595, 2023). "Collectively, our preclinical and clinical findings suggest that VHL-KO or VHL− tumor cells drive cooperative metastasis by inducing the proliferation of VHL-WT or VHL+ cells." (PMID 37069149, 2023). "In another study, peptidic PROTACs composed of ligands for MDMX protein and VHL were conjugated to gold(I) via thiol-gold interaction and self-assembled to nanoparticles (Nano-MP@PSIs) for tumor-specific MDMX-degrading PROTAC delivery." (PMID 36839734, 2023). "The WT VHL gene is known to induce growth arrest by restoring cell entry into G0 or the quiescent state and to suppress tumor growth." (PMID 37762376, 2023). "This study seeks to understand the metastatic crosstalk at play between the VHL+ and VHL− tumor cells in ccRCC." (PMID 37069149, 2023). "In what follows, we provide more detailed information on two exemplary cases, namely, the first oncogene (NRAS) and the first tumor-suppressor (VHL) featured in this ranking." (PMID 37834310, 2023). "Further, the prognostic performance of immune subtype is superior to that of traditional tumor markers (VHL, AHNAK2, and CDKN2A) in ccRCC patients." (PMID 37315301, 2023). "We have previously shown that knockdowns of LC3C in 786-O VHL(+) and A498 VHL(+) cells induced tumor formation in orthotopic xenografts." (PMID 37003503, 2023). "The study of genetic factors that can trigger the development of tumours through massive sequencing can help to modify the natural evolution of genetic tumoral diseases like VHL, in a personalized way." (PMID 37843608, 2023). "Many studies have further revealed that ccRCC is a hyper-angiogenic tumor due to VHL inactivation-induced overexpression of VEGF." (PMID 37460463, 2023). "Congruent with the CTC results, multiplex immunofluorescence (MIF) stains revealed that intravascular tumor cells in the RC primary tumors and lung metastases were predominantly VHL+ cells." (PMID 37069149, 2023). "Periostin (POSTN), a soluble protein overexpressed and secreted by VHL non-expressing (VHL−) cells, promoted metastasis by enhancing the motility of VHL-WT cells and facilitating tumor cell vascular escape." (PMID 37069149, 2023). "Belzutifan (Welireg®) is a recently developed HIF2a inhibitor, uniquely designed to counteract the constitutive activation of HIF in VHL disease-related neoplasms." (PMID 36980625, 2023). "In cellular physiology, the VHL protein acts as a tumor suppressor by targeting hypoxia-inducible factors (HIFs) for degradation." (PMID 36991452, 2023). "Longitudinal analyses of vascular invasion of tumor cells in our metastatic mixed tumor model showed that VHL-KO cells invaded early into the circulation and their presence enhanced the subsequent escape of VHL-WT cells into the circulation." (PMID 37069149, 2023). "In this context, one interesting link between FBXL4 and VHL has been made in a genome‐wide CRISPR screen for synthetic lethality with common tumour suppressors." (PMID 37102372, 2023). "In this study, we analyzed the biochemical and tumorigenic activities of the L169P VHL variant, including protein stability, the degradation of alpha subunits of HIF, hypoxic tension and tumor-growth-suppressive ability." (PMID 37762376, 2023).
tumor (continued). "Corroborating the in vitro results, the 786-O cells with a restored expression of either WT or L169P VHL exhibited slower growth rates in vivo, resulting in a significantly lower terminal tumor size and weight compared to the parental 786-O xenografts." (PMID 37762376, 2023). "Accumulating evidences have suggested that VHL acts as a tumor suppressor in many types of human cancers." (PMID 36813772, 2023). "Together, our results uncover a previously unrecognized function of CDK1 to promote tumor progression through destabilizing pVHL in cancer harboring wild-type VHL." (PMID 36813923, 2023). "While substrates of VHL have been identified, its tumor suppressive role remains to be fully understood." (PMID 37850636, 2023). "This is reasonable given that this chromosome contains four tumor-suppressor genes (VHL, PBRM1, BAP1, and SETD2) that are crucial for cellular survival." (PMID 37842234, 2023). "Borderline statistically significant p-values were observed when assessing the association between the evaluated SNPs (rs1642742 and rs779805 in the VHL tumor suppressor gene) and increased tumor size." (PMID 36835190, 2023). "Among the genomic biomarkers able to discriminate transformed tumours (hEMT, MES) from the epithelial state, we identified genes that have been previously linked with cell migration, invasion and EMT, such as RB1, VHL, ERBB2, ARHGAP26, PRDM1, APC." (PMID 36774358, 2023). "In this study, we pursued two additional assays besides those previously reported to further clarify the potential oncogenic role of L169P VHL in hypoxia regulation and in tumor growth suppression." (PMID 37762376, 2023). "Von Hippel–Lindau (VHL) is a tumor suppressor that functions as the substrate recognition subunit of the CRL2VHL E3 complex." (PMID 37850636, 2023). "An immediate issue is how to detect the exosomes produced by ccRCC tumor cells and more specifically, the VHL(−) exosomes in patients’ blood." (PMID 38139136, 2023). "VHL, as a E3 ligase, has been reported to induce the protein degradation of β-catenin and P65 to inhibit tumor progression." (PMID 36813772, 2023). "VHL expression in the primary tumor of #22 was highly heterogeneous, with VHL+ cells juxtaposed to VHL− cells." (PMID 37069149, 2023). "There was much lower VHL level but endowed with higher HIF1A, LEPTIN, UCP1 and phosphorylated HSL protein expression in tumour associated adipose tissue as well." (PMID 37620316, 2023). "NPT-BEZ235, a dual inhibitor of PI3K and mTOR, increased ciliogenesis of VHL-deficient hTERT-PRE1 cells and reduced tumor burden in a mouse xenograft model of RCC." (PMID 37780208, 2023). "Studies have reported that UBE2S targets VHL for degradation to regulate tumor growth and metastasis in various cancers." (PMID 37563971, 2023). "We aim to elucidate the molecular mechanism by which PIN1 and CDK1 cooperatively modulate pVHL stability, contribute to tumor progression and explore their therapeutic potential in the treatment of cancers with wild-type VHL including TNBC." (PMID 36813923, 2023). "The inactivation of VHL is accompanied by the accumulation of hypoxia-inducible factors (HIFs) in the tumour microenvironment, their interaction with NO synthases, the regulation of intratumoural NO production, and the development of renal tumours." (PMID 38136342, 2023). "Longitudinal analysis of circulatory tumor cells (CTCs) in mice bearing mixed RC renal tumors revealed that VHL-WT was the predominant population of tumor cells that escaped into the circulation, especially at later times after 4 weeks of tumor growth." (PMID 37069149, 2023). "Orthotopic tumor formation was monitored through longitudinal bioluminescence imaging (BLI), which showed a drastic loss of tumorigenicity by VHL overexpression." (PMID 35159281, 2022). "VHL is an autosomal inherited rare tumor disease with an estimated annual birth incidence of 1/36,000." (PMID 35163250, 2022).
tumor (continued). "Due to the downstream inappropriate pro-angiogenic upregulation occurring in the setting of dysfunctional pVHL, the highly vascular neoplasms present in VHL disease are known to overproduce such angiogenic peptides." (PMID 36358730, 2022). "The optimized protocol herein leverages tumor-derived somatic data and signature LOH profile as strong supporting evidence in the evaluation of pathogenicity of germline VHL variants." (PMID 35774415, 2022). "Genotype–phenotype correlations in VHL disease suggest that oxygen-dependent HIF regulation by VHL mutant proteins, as well as HIF-independent VHL functions, modulate the risk of tumor development." (PMID 35205407, 2022). "VHL regulates the transcription of Spp1, a hypoxia-responsive gene in tumor cells, via inhibiting HIF1α-mediated glycolytic metabolism in AMs, indicating that VHL is a key regulator of alveolar macrophages in PF." (PMID 36452229, 2022). "Among the various tumor types, RCC has frequent mutational loss of the VHL tumor suppressor contributing to poor prognosis." (PMID 35937460, 2022). "The inappropriate accumulation of HIF2 drives tumor formation by VHL tumor suppressor protein (pVHL)–defective ccRCC." (PMID 35357972, 2022). "Our results offer pharmacological avenues to sensitize therapy-resistant VHL tumours by focusing on the mitochondria." (PMID 35760869, 2022). "First diagnostic criteria—1964: patients with no family history of VHL disease and two related tumors (two CHBs alone or only one combined with a visceral tumor), or with family history and at least one VHL-related tumor." (PMID 36358771, 2022). "The consequence of VHL loss of function is constitutively stabilized HIF-1α and HIF-2α, a first step in tumor initiation that increases angiogenesis and drives widespread dysregulation of cellular metabolism." (PMID 36192773, 2022). "Similar genetic changes are seen in sporadic ccRCC, however, tumor heterogeneity is generally less diverse in VHL and lesions develop later in life in the setting of sporadic ccRCC." (PMID 36421797, 2022). "First, using orthotopic injection of luciferase-labeled 786-O sublines, we confirmed that persistent extinction of VHL expression is required for ccRCC tumor maintenance." (PMID 35159281, 2022). "In the case of VHL, gene therapy aimed at regaining VHL expression with delivery methods such as plasmid and adenovirus was shown to retard tumor growth in mice." (PMID 35159281, 2022). "Early studies revealed that the von-Hippel-Lindau (VHL) tumor suppressor is an obligate substrate of CCT." (PMID 35602608, 2022). "As a tumor suppressor, VHL functions as an E3 ubiquitin ligase to mediate the proteasomal degradation of hypoxia-inducible factor (HIF)." (PMID 36611966, 2022). "In preclinical analyses evaluating potential factors contributing to tumor growth in VHL-null Drosophila and human clear cell RCC, synthetic lethality was discovered between VHL and the cell cycle regulators cyclin-dependent kinases 4 and 6 (CDK4/6)." (PMID 36358730, 2022). "We showed that by calculating the median transcription values of the four ccRCC tumour suppressors of 3p25 and 3p21 chromosomal loci—VHL, SETD2, PBRM1, and BAP1–, complemented that of the p14ARF, normal and ccRCC tissues can be distinguished." (PMID 35586183, 2022). "This Review describes mechanisms involving the VHL gene product in oxygen sensing, protein degradation, and tumor development and current therapeutic strategies targeting these mechanisms." (PMID 36106637, 2022). "Overexpression of miR-155 induced tumor angiogenesis and promoted breast tumor growth through targeting and downregulating the Von Hippel-Lindau (VHL) tumor suppressor." (PMID 35434143, 2022). "Clear cell RCC frequently upregulates the VEGF pathway to propagate angiogenesis via inactivation of the von Hippel–Lindau (VHL) tumor suppressor gene." (PMID 36291789, 2022).
tumor (continued). "Our results define a new manner on how inactive VHL affects tumor progression and provide new perspectives for the therapeutic strategies for patients with ccRCC." (PMID 35637958, 2022). "Mutated VHL, as often observed in ccRCC, leads to stabilization of HIF-1/2α that activates target genes underlying ccRCC-associated alterations in tumor metabolism, genome-wide epigenetic changes, tumor growth and metastasis." (PMID 35408930, 2022). "The mutations of NF2 and VHL are present in both the PDX model and the corresponding primary tumor in the Tübingen cohort (crossed squares)." (PMID 35800063, 2022). "The gene product is the VHL protein (pVHL), which consists of two isoforms, both of which have tumor-suppressing activity." (PMID 36358771, 2022). "One treatment strategy in ccRCC is to inhibit the VEGF signaling that is commonly dysregulated following VHL gene inactivation within RCC tumor cells and would otherwise stimulate endothelial cell growth and angiogenesis." (PMID 36180422, 2022). "In humans, the VHL gene is located next to other tumor suppressors (e.g., PBRM1, BAP1 and SETD2) on chromosome 3p." (PMID 35463327, 2022). "When only considering these two mutated genes, the rate of conserved mutations between patient tumor and PDX tissue was very high, resulting in 100% for NF2 and 100% for VHL, respectively." (PMID 35800063, 2022). "VHL/HIF-1α is a common signaling pathway in KIRC, and mutational inactivation of VHL leads to overexpression of HIF-1α in KIRC, inducing a tumor hypoxic microenvironment that is associated with poorer tumor-specific survival." (PMID 36119517, 2022). "The tumor suppressor function of VHL has been demonstrated in nude mice where restoration of its function inhibits tumor formation." (PMID 35223522, 2022). "VHL inactivation results also in changes in the tumor secretomes that can affect T cells functions, for example due to enhanced levels of the MnSOD2 enzyme that cause redox stress in T cells thereby impairing their functionality." (PMID 35663987, 2022). "Collectively, these results indicate that VHL-null ccRCC cells are sensitized to sorafenib when combined with LONP1 inhibitor bortezomib, leading to a profound tumour growth defect in vivo that was associated with increased levels of mitochondrial content." (PMID 35760869, 2022). "Von Hippel-Lindau (VHL) disease is a rare, autosomal dominant inherited syndromethat affects the germline of the VHL gene, a tumor suppressor gene." (PMID 35795602, 2022). "In most ccRCC tumors, CA IX is frequently expressed at high levels due to the functional inactivation of the VHL tumor suppressor gene that generates defective pVHL protein unable to negatively regulate HIF-1α." (PMID 35109923, 2022). "While previous studies proved that VHL restoration in 786-O inhibited tumor formation in subcutaneous models, our study confirmed this phenomenon in the orthotopic site." (PMID 35159281, 2022). "Inactivation of the VHL tumor suppressor gene due to genetic alterations of wild type alleles has been identified in VHL patients as well as in sporadic ELSTs." (PMID 35546652, 2022). "Somatic mutations in VHL, the most frequently mutated gene in RCCs, were identified in 10 RCC organoids and matched tumours." (PMID 35802820, 2022). "At present, there are few experimental studies on the VHL gene in vitro, adding tumor suppressor genes in tumor cells and analyzing the changes, which is helpful to reveal the molecular mechanism of tumor development." (PMID 35035522, 2022). "There was a higher M2:M1 ratio in cluster 1 (SDHx, VHL, FH, n = 27) tumours compared to cluster 2 (RET, n = 6) (P = 0.017) and a lower proportion of CD8 cytotoxic (Tc) lymphocytes in PPGLs with a known genetic diagnosis (P = 0.047)." (PMID 35975974, 2022). "Due to the abnormality of the VHL gene, the VHL-HIF-HRG signaling pathway is continuously activated, causing tumor cells to synthesize and secrete a large amount of angiogenic factors." (PMID 35035522, 2022).